CXCL12 (C-X-C motif chemokine ligand 12)
Diseases named in the same sentence as CXCL12 in open-access papers (continued):
Sharing a sentence is not in itself a finding about the gene and the disease.
cancer (continued). "A transcript of 383 bps corresponding to the CXCL12 gene was detected in the less aggressive carcinoma cell lines MCF-7 and PMC42, in the normal cell line HB4a and in the modified normal cell line HB4aC3.6 with ERBB2 overexpression." (PMID 20109227, 2010). "The CXCR4/CXCL12 biological axis has been postulated to have an important in supporting cancer stem cells." (PMID 19563666, 2009). "Organs to which these cancers metastasize secrete CXCL12, the unique ligand for CXCR4, which stimulates invasion and metastasis to these sites." (PMID 19325924, 2009). "We compared 231-control cells to MDA-MB-231 cells stably expressing CXCR4 (231-CXCR4) or CXCR7 (231-CXCR7) to assess effects of CXCL12 chemokine receptors on cancer cells in mediating adhesion onto the microfluidic endothelium." (PMID 19484126, 2009). "For each of the three cancer cell types, adhesion preference was towards CXCL12-treated endothelium over the corresponding untreated endothelium in the same device (p<0.05)." (PMID 19484126, 2009). "The microfluidic vasculature reproduces preferential adhesion of circulating cancer cells to endothelia in organs and tissues with high levels of CXCL12 in vivo." (PMID 19484126, 2009). "We determined that pro-metastatic effects of CXCL12 on circulating cancer cells are mediated at least in part through vascular endothelium." (PMID 19484126, 2009). "The level of adhesion of the three cancer cell types was statistically different on both the CXCL12-treated and untreated endothelium (p<0.05) with the adhesion of 231-CXCR4 and 231-CXCR7 cells being significantly greater than 231-control cells (p<0.05)." (PMID 19484126, 2009). "AMD3100 was able to return adhesion to baseline values at both flow rates, showing that the enhanced adhesion selectivity of circulating cancer cells is due to CXCL12 signaling through CXCR4 on the vascular endothelium." (PMID 19484126, 2009). "For all three cancer cell types, adhesion selectivity towards CXCL12-treated endothelium increased with increasing flow rates among 0, 0.50, and 2.50 dyn cm−2 (p<0.05)." (PMID 19484126, 2009). "Ourprevious observations that DIM downregulates CXCR4 and CXCL12 in breast andovarian cancer cells represent a novel mechanism for the chemoprotectiveeffects of this phytochemical." (PMID 19325924, 2009). "More recent studies have suggested that CXCR4 is expressed on various other cancer cells and its expression stimulated migration of cancer cells towards a CXCL12 gradient established in specific target organs for metastases." (PMID 19563666, 2009). "Various studies have shown significant CXCL12 concentrations in thefluid-filled cavities through which many cancers disseminate, and at tissuelocations in which metastases characteristically develop." (PMID 18779872, 2008). "Recently, it has also been reported that CXCL12 is highly expressed in several internal organs that are the primary targets of cancer cell metastasis, and that CXCR4 is overexpressed on the surfaces of several types of cancer cells." (PMID 19787093, 2008). "As well aspromoting the migration of cancer cells and their invasion through physicalbarriers as well as adherence to target structures, CXCL12 can act upon CXCR4on the cancer cells to promote cancer cell growth along with other mitogenicfactors." (PMID 18779872, 2008). "CXCL12 in normal tissue attracts the CXCR4 on the cancer cells, stimulating cell proliferation and inducing angiogenesis." (PMID 18983683, 2008). "Since that time,the CXCL12/CXCR4 axis has been shown to be important in the progression andspread of more than 25 different cancers." (PMID 18779872, 2008). "The characterization of the CXCR4/CXCL12 chemokine axis in five UM cell lines have shown significant reduction of cancer cell migration in vitro." (PMID 18001467, 2007). "Recent reports suggest a role for CXCR4 and its ligand CXCL12 in the malignant behaviour of cancer cells." (PMID 17925864, 2007).
cancer (continued). "This suggests that heparin therapy reduces the potential of CXCL12 to ‘capture’ cancer cells within breast tissues." (PMID 17726466, 2007). "Both the expression of CXCR4 on cancer cells and CXCL12 on the apical surface of vascular endothelium were examined to assess the role played by chemokines in the anticancer activity of heparinoids." (PMID 17726466, 2007). "In a number of cancer types, binding of its cognate ligand CXCL12 was reported to mediate directed migration of cancer cells to sites of metastasis." (PMID 17925864, 2007). "To mimic this phenomenon in vitro, we explored the effect of CD164 on the ability of cancer cells to invade reconstituted extracellular matrix in response to CXCL12." (PMID 16859559, 2006). "More recent studies have suggested that CXCR4 is expressed on various other cancer cells and its expression stimulates migration of cancer cells towards a CXCL12 gradient established in specific target organs." (PMID 17083723, 2006). "Furthermore, these compounds disrupt key molecular pathways like the CXCR4/CXCL12 axis, which is crucial for cancer cell migration and metastasis." (PMID 40018013, 2025). "The elevated cancer cell concentrations in this region enhance production of CXCL12." (PMID 40464993, 2025). "The CXCL12/CXCR4 axis is involved in multiple critical processes, including cell proliferation, survival, migration, invasion and metastasis, and is associated with more than 20 different types of cancer." (PMID 40909292, 2025). "Pseudo-time analysis suggested that CAFs with high ALDOA and CXCL12 expression represent terminal subtypes differentiated from normal fibroblasts, indicating that during the malignant progression of cancer, normal fibroblasts transform into activated cancer-associated fibroblasts." (PMID 41584584, 2025). "Additionally, CXCL12 expression was related to stage, survival, immune subtype, and molecular classification across cancers." (PMID 40166682, 2025). "Moreover, CXCL12 from senescent thyroid cancer cells contributed to cancer invasion and metastasis to lymph nodes." (PMID 40862837, 2025). "Indeed, the CXCL12/CXCR4 signaling pathway is well established for its role in metastasis, and CXCR4 overexpression has been associated with cancer cell proliferation, apoptosis resistance, and local invasion." (PMID 40362664, 2025). "Bioinformatic scrutiny revealed the pivotal role of CXCL12 in pan-cancer." (PMID 40166682, 2025). "Furthermore, CXCL12 by binding to its receptor on nearby stem cells (CD44+CD24-) accelerates the development of cancer by encouraging proliferation and malignant initiation." (PMID 40940764, 2025). "Thus, the CXCL12/CXCR4 axis functions as a critical node linking stromal activation with cancer cell invasion and profound immune dysfunction." (PMID 40909268, 2025). "PPI regulatory networks for CXCL12 were strategically designed, investigating its activation/inhibition mechanisms, revealing its enriched functional pathways, and assessing its activity at a cellular level in select cancers." (PMID 40166682, 2025). "Additionally, investigating the pan-cancer context via unpaired sample analysis in the TCGA-GTEx dataset revealed a downregulated CXCL12 expression in cancerous tissues (e.g. BLCA, BRCA, CESC, etc.)compared to their corresponding normal counterparts." (PMID 40166682, 2025). "The CXCR4/CXCL12 axis is a crucial mechanism in cancer progression, especially in TNBC." (PMID 41002447, 2025). "The CXCR4/CXCL12 signaling pathway is gaining attention as a promising target for cancer therapy." (PMID 40142155, 2025). "Cancer-specific and stimulus-responsive nanocarriers could achieve precise drug release in CXCL12-rich environments." (PMID 41002447, 2025). "Furthermore, the CXCR4/CXCL12 axis plays a multifaceted role in cancer, including leukemic stem cell homing and signaling." (PMID 40698080, 2025).
cancer (continued). "Over-expression of hsa-miR-135b and subsequent down-regulation of CXCL12 might reduce the chemotactic and angiogenic capabilities of cancer cells, potentially inhibiting metastasis." (PMID 40426863, 2025). "Likewise, in cancer cell migration, while CXCL12 and Ephrin signalling have been linked to metastasis, the specific role on invasive behaviour of their local signalling at the ciliary compartment remains poorly characterised." (PMID 40661145, 2025). "The primary focus was on CXCL12, examined comprehensively within multiple cancers." (PMID 40166682, 2025). "However, GPR15LG significantly enhanced CXCL12-directed migration, suggesting a potential role in cancer cell migration and disease progression." (PMID 40394646, 2025). "IL-6 and CXCL12, secreted by cancer cells, are responsible for glia-mediated pain suppression." (PMID 40427098, 2025). "In another microfluidic model, the adjacent culture of cancer associated fibroblasts (CAFs) in collagen type I hydrogels and endothelial monolayers (vessel analogs) demonstrated that CAF-secreted C-X-C motif chemokine ligand 12 (CXCL12) enhanced endothelial permeability." (PMID 40678259, 2025). "By comparing the effects of growth factor treatment on the control and SORL1 knockdown cell lines, we identified that SORL1 was involved in the cancer cell growth stimulated by CXCL12, BDNF, FGF1, and EGF1 in OVCAR8 cells and by BDNF, FGF1, and EGF1 in KRCH31 cells." (PMID 39858026, 2025). "In addition, CXCL12 attracts cancer cells to tissues rich in this ligand, which facilitates metastasis." (PMID 40362280, 2025). "This process confers cancer cells the capacity to intravasate, enter the bloodstream, and extravasate, thereby contributing to homing, colonization and metastasis in organs that secrete CXCL12/SDF-1, the ligand of the chemokine receptor CXCR4." (PMID 40307933, 2025). "Future research, targeting CXCL12 expression and immune infiltrates within a cancer demographic, may clarify these findings." (PMID 40166682, 2025). "CXCR4, the receptor for CXCL12, is also being targeted for cancer therapy in the clinic." (PMID 39780187, 2025). "Thus, the CXCL12/CXCR4 axis has become a compelling target for novel cancer therapies to enhance treatment efficacy and prevent metastasis." (PMID 39070795, 2024). "Together, these results underscore how different cancer cells respond to the CXCL12/HMGB1 heterocomplex enhancing directional cell migration and invasion, which depends on the balance between maintaining HMGB1 in its reduced form and promptly removing CXCL12 from the microenvironment." (PMID 38803493, 2024). "This is because CXCL12 is able to activate monocytes-derived immunosuppressive macrophages with lower capability of T lymphocyte stimulation which in turn results in enhanced migration and accumulation of macrophages in cancer cells." (PMID 39003350, 2024). "The activation of CXCL12/CXCR4 axis also plays an important role in the formation of cancer pain." (PMID 39654896, 2024). "Additionally, TGM2-dependent covalent CXCL12-Keratine 19 heterodimers can coat cancer cell surfaces, potentially interfering with T-cell-mediated immune responses, suggesting a role for CK-19 in immune regulation." (PMID 38813379, 2024). "Interestingly, for certain cancers such as leukemia, adipocytes from multiple sources (subcutaneous, visceral, muscular, pulmonary) secrete chemotactic signals like the cytokine CXCL12, which attract tumor cells." (PMID 39518143, 2024). "Due to the critical functions of CXCL12, its dysregulation has further been correlated with a variety of pathological conditions, including viral infections, neurodegenerative diseases, and cancer." (PMID 39662834, 2024). "Notably, the presence of both pro-inflammatory (e.g., IL17A) and homeostatic (e.g., CXCL12) factors underscores the complex interplay between chronic inflammation and cancer progression in the intestinal microenvironment." (PMID 39767563, 2024).
cancer (continued). "Furthermore, specific targeted intervention of the related proteins in the crosstalk signal axis of CXCL12/STAT3 can pave new avenues for cancer treatment." (PMID 38920657, 2024). "While known to attract CD8+ T cells, acting to sequester and misdirect them away from tumoral cells and towards CAFs, recent work suggests that CXCL12 may also be necessary for T cells to eliminate cancer cells." (PMID 38339310, 2024). "The CXCL12 overexpressed in some tissues and organs is a key niche factor that nurtures the pre-metastatic niches and recruits tumor cells to these niches, thereby fostering cancer cell aggression and metastatic capabilities." (PMID 39766230, 2024). "However, chemokine receptor CXCR4 has a sole natural ligand, CXCL12, and, in cancer, this interaction can facilitate metastasis to secondary sites, promote tumour growth, and therapy resistance." (PMID 39204345, 2024). "Therefore, CXCL12-coated cancer cells surrounded by CXCR4-expressing CAFs inhibited both CTL access to the TME and their interaction with malignant cells." (PMID 39596815, 2024). "In addition to CXCL12, there are other chemokines that hold promise for regulating the migration of cancer cells, such as CXCL8, CXCL16, CCL2, and CXCL10." (PMID 39715221, 2024). "CXCL12 was highly expressed in cancer tissue in the TLS high-grade group." (PMID 38767772, 2024). "Therefore, inhibition of the CXCL12/CXCR4 axis can be a potential therapeutic target in cancers and ADs." (PMID 39070795, 2024). "Besides the CXCR4/CXCL12 axis, different chemokine receptors have also been shown to play a role in cancer." (PMID 39698539, 2024). "Importantly, the addition of CXCL12 increases chemotaxis and participates in a positive feedback loop to increase cancer cell expression of CXCR4." (PMID 39766093, 2024). "The results may reflect clinical biology or methodological differences, as CXCL12 expression varies in pattern among individual cancer types." (PMID 37966614, 2023). "Functional CXCL12 knockdown or the CXCR4 antagonist AMD3100 decreases the survival of cancer cells." (PMID 36980201, 2023). "In 30 (63.8%) of the specimens, cancer cells were positive for CXCL12 staining." (PMID 36300800, 2023). "Both cancer cells and HSCs use similar pathways to induce dormancy, such as the CXCL12/CXCR4 axis." (PMID 37182144, 2023). "Most research on the role of CXCL12 in disease has been focusing on cancer." (PMID 36725964, 2023). "Moreover, CAFs-secreted CXCL12 recruits monocytes and induces their differentiation into M2-like macrophages, a crucial factor in enhancing cancer stemness and resistance to chemotherapy." (PMID 37821959, 2023). "Targeting the CXCL12 signal axis is a promising therapy for cancer." (PMID 36639681, 2023). "Alternatively, metformin may preferentially target cancer cells with aberrant mTOR activation induced by the CXCL12/CXCR4-mediated pathway." (PMID 37760498, 2023). "Finally, CXCR4 and its ligand, CXCL12, can promote metastasis by preventing anoikis in cancer cells." (PMID 36980201, 2023). "The CXCL12/CXCR4 axis plays a critical role in the pathogenesis of cancer metastasis." (PMID 37227446, 2023). "The CXCL12/CXCR4 biological axis plays an important role in the malignant progression of cancer." (PMID 38057830, 2023). "For example, TPRGs CDK1 and CXCL12 are expressed in both T cells and various cancer cells." (PMID 37077919, 2023). "In addition, we also found that CXCL12 is expressed in muscle cells adjacent to cancer cells within tongue OSCC tissues." (PMID 36300800, 2023). "These CAFs-derived molecules, IGF1/2, CXCL12 and beta-hydroxybutyrate, increased ROS level after radiation, thereby enhancing protein phosphatases 2A activity, inhibiting mTOR activation, and increasing autophagy in cancer cells." (PMID 37600785, 2023).
cancer (continued). "This may be a new perspective to explore the immune mechanism and immunotherapy for cancer.Notably, studies have reported Notch signaling has been implied in mediating chemotaxis system CXCL12/CXCR4 promoted carcinoma metastasis and multiple myelom." (PMID 37932706, 2023). "Studies have shown that CXCL12 can induce drug resistance in cancer." (PMID 38057830, 2023). "In particular, CXCL12 was expressed to high extents (cutoff = 10.5 cells/punch in primary, cutoff = 10 cells/punch in recurrent cancer, respectively) in 32 out of 43 primary and in 29 out of 41 recurrent cancer biopsies." (PMID 37966614, 2023). "TAMs generate chemokines, including CXCL8 and CXCL12, which may instruct cancer cells to acquire a CSC-like character and sustain stemness in oral squamous, HCC, and renal cell carcinoma." (PMID 37211559, 2023). "Moreover, CAF-derived CXCL12 can bind to cancer cell-derived CXCR4, activating the CXCR4/CXCL12 axis and promoting CSC phenotypes, including its proliferation, invasion and metastasis." (PMID 38455361, 2023). "Additionally, this CAF-derived CXCL12 mediates inhibition of PTEN which is crucial for cancer cell proliferation." (PMID 37065872, 2023). "In the network, eight genes related to the apoptotic process and cell migration, including Mmp9, Cxcl12, Cdh1, Fap, Itga6, Mdk, Aif1, and Mif, were downregulated with co-treatment, which may play vital roles in inhibition of cancer progression and cell death." (PMID 36765032, 2023). "The CXCL12/CXCR4 cascade has been identified as a vital component in guiding embryological migration of primordial germ cells, and is implicated in the predisposition of testicular germ cells to cancer." (PMID 36614308, 2023). "In PDAC, cancer cells encourage CAFs to produce CXCL12 by secreting TNF-alpha, TGF-beta and others." (PMID 37834436, 2023). "CXCL12/CXCR4 cascade in FAP+CAF also contributed to cancer cell proliferation." (PMID 37784082, 2023). "CXCL12 has been reported to recruit multiple types of cancer to bone." (PMID 37025604, 2023). "The results demonstrated that CAFs cause infiltration of MOs via the CXCL12/CXCR4 pathway followed by their differentiation to M2 phenotype, which implies the potential of CXCL12-mediated macrophage recruitment as a novel target for cancer therapy." (PMID 38313431, 2023). "Moreover, previous studies have suggested that curcumin can interfere with the metastasis of cancer cells by inhibiting the CXCL12/CXCR4 axis." (PMID 38004606, 2023). "We have provided clear evidence suggesting that DPP-4 inhibition could facilitate cancer growth, metastasis, and chemoresistance via the accumulation of CXCL12, the endogenous substrate of the DPP-4 enzyme." (PMID 37760498, 2023). "CXCR4, a chemokine receptor expressed by most cancer types, including cancers of epithelial, mesenchymal and hematopoietic origin, has a critical role in cell migration and metastasis to organs that secrete its ligand, CXCL12, also known as stromal cell-derived factor-1 (SDF-1)." (PMID 37371036, 2023). "CXCL12 promotes cancer development by two main mechanisms: i) directly activating signaling pathways involved in cancer cell growth, metastasis, and angiogenesis, and ii) indirectly promoting metastasis by recruitment of CXCR4+ cancer cells to CXCL12-expressing organs." (PMID 37251376, 2023). "Mixtures of CXCL4 and CXCL12 or obligate CXCL4•CXCL12 heterodimers inhibited CXCL12-induced migration of breast MDA-MB-231 cancer cells, increased Ca2+ release and activated downstream signaling of CXCR4 but not of CXCR3, highlighting its role in the limitation of cancer progression." (PMID 37446102, 2023). "The microscopic CXCL12-rich cancer stroma may create immune-privileged sites when expressed intratumorally." (PMID 37966614, 2023).